EGFR (epidermal growth factor receptor)
Diseases named in the same sentence as EGFR in open-access papers (continued):
Sharing a sentence is not in itself a finding about the gene and the disease.
cancer (continued). "This study points to an alternative possibility in the fight against aggressive cancer by targeting EGFR with furfuryl derivatives of 4-allyl-5-[2-(4-alkoxyphenyl)quinolin-4-yl]-4H-1,2,4-triazole-3-thiol." (PMID 31374910, 2019). "Skin reactions are ascribed to EGFR expressed on basal epidermal keratinocytes, sebaceous and eccrine sweat gland cells, and various cancer cells." (PMID 30646927, 2019). "From several clues that suggest connections between cancer metabolism and signaling pathways in HNC, a more detailed understanding of how cancer metabolism is mechanistically involved in EGFR-mediated signaling in HNC is required." (PMID 30700700, 2019). "Src kinase has been reported to interact with activated EGFR to form a complex that increases EGFR tyrosine phosphorylation and accelerates cell transformation and cancer development." (PMID 30947731, 2019). "In this study, we found that cell-substratum adhesion transactivated EGFR via Src signaling in some cancer cells." (PMID 31615015, 2019). "The abnormal expression or activation of EGFR and its downstream signaling pathways can promote malignant processes, invasion, and drug tolerance in many human cancers." (PMID 30759826, 2019). "EGFR, ERBB3, MMP20, MMP27, MCL1, BCL2A1 and BAK1 appear to be important genes for cancer progression due to their frequent association with recurrent cancer-related genes in women." (PMID 31205821, 2019). "Overexpression and aberrant activity of the EGF and EGFR have been observed in various cancer types." (PMID 30971297, 2019). "In a forthcoming study, we will apply our framework to assess the efficiency of EGFR inhibitors in the treatment of different types of cancer." (PMID 31016574, 2019). "The treatment of cancer cells with potent EGFR TKIs has been shown to increase BimL and BimEL expression levels." (PMID 31374910, 2019). "This resulted in a more interpretable and robust model with high generalized predictive performance throughout various EGFR inhibitors and cancer types." (PMID 30621238, 2019). "Oncogenic activation mutations in upstream kinases BRAF, MEK, EGFR and HER2 are frequently observed in cancer." (PMID 31407663, 2019). "Defects in E-Cadherin have displayed epithelial–mesenchymal transition (EMT) hallmarks and invasive phenotypes through RhoA GTPase in cancer and dysregulated EGFR signaling." (PMID 31805710, 2019). "Altered levels of EGFR play an important role in the growth, invasion, adhesion, and angiogenesis of numerous cancers." (PMID 30808960, 2019). "Epidermal growth factor receptor (EGFR) has been reported to be expressed in human cancers of epithelial origin." (PMID 31878324, 2019). "To show that EGFR ligands do not affect the phosphorylation of ErbB3, we investigated the phosphorylation of EGFR and ErbB3 in cancer cell lines treated with EGF, transforming growth factor-α (TGF-α), or heparin-binding EGF-like growth factor (HB-EGF)." (PMID 31615015, 2019). "EGFR is overexpressed in several cancers, including colorectal cancer, lung cancer, and head and neck cancer." (PMID 31609054, 2019). "Epidermal growth factor receptor (EGFR)-targeted gene downregulation is effective for cancer therapy." (PMID 31221991, 2019). "EGFR is known to be critically involved in tissue development and homeostasis as well as in the pathogenesis of cancer." (PMID 30659329, 2019). "It is known that c-Src interacts with EGFR inducing its phosphorylation and that the increased activity/overexpression of c-Src is related to cancer progression, since its interaction with EGFR/Her2 enhances mitogenic signaling pathways." (PMID 31466222, 2019). "Specifically, anti-EGFR IgE triggered superior ADCC functions (70%) against cancer cells, compared with the corresponding IgG1 (30%)." (PMID 31544825, 2019).
cancer (continued). "Previous studies have indicated that AR is able to regulate the activation of extracellular signal-regulated kinase (ERK) through EGFR, leading to the progression of cancers." (PMID 31370819, 2019). "Co-encapsulating integrin αvβ3 inhibitor and EGFR inhibitor further improved the drug delivery system, leading to superior anti-cancer effects and reduced systemic toxicity." (PMID 31316001, 2019). "PCC-0208027 is a novel tyrosine kinase inhibitor that has a strong inhibitory effect on epidermal growth factor receptor (EGFR)- or HER2-driven cancers." (PMID 30952931, 2019). "Although EGFR inhibitors are effective in treating cancer, the early onset of drug resistance limits their therapeutic success." (PMID 30987191, 2019). "SDS-PAGE electrophoresis showed no Akt and Erk activation in cancerogenic E705 cells, leading us to think that the difference in the vitality between healthy and cancer cells is due to EGFR downstream targets activation in the former." (PMID 31209580, 2019). "Other novel, highly scoring gene pair predictions that included cancer associated genes included PARP1 with PBRM1, BRCA2, ARID1A and APC as well as PIK3CA with MAP2K1, ABL1 and EGFR." (PMID 30995217, 2019). "Again, tumors with high EGFR expression responded better to moderately accelerated radiotherapy, compared with low EGFR-expressing carcinomas." (PMID 30652016, 2019). "Here, NMR of hyperpolarized [1-13C]pyruvate has proven to be appropriate for monitoring the early response of both carcinoma cell lines analysed to treatment with 213Bi-anti-EGFR-MAb." (PMID 31165773, 2019). "Studies have suggested that carcinomas with elevated EGFR expression had significantly enhanced malignant biological behavior, and was independent risk factor for poor prognosis." (PMID 33817143, 2019). "For example, the half-life of the colony stimulating factor 1 receptor (CSF-1R) in macrophages is less than 1 h, whereas for the epidermal growth factor receptor (EGFR) in carcinoma cells, it is 24 h." (PMID 31600876, 2019). "In both EJ28Luc and LN18 carcinoma cells treatment with 213Bi-anti-EGFR-MAb triggered a significant increase in lactate/pyruvate ratios, as measured with hyperpolarized [1-13C]pyruvate." (PMID 31165773, 2019). "Aberrant activation of the EGFR/ERK pathway has been confirmed in various carcinomas and is relative to cancer development." (PMID 30487162, 2019). "Recent studies showed that distal carcinomas were more likely to be HER2 or EGFR positive than proximal carcinomas despite the tests used." (PMID 30858756, 2019). "Our results confirm that can225IgG bound to canine EGFR on cells specifically and was internalized within 6 hours of incubation in EGFR expressing cancer cells." (PMID 29721181, 2018). "The most common individual cancer drugs causing DIILD were identified as bleomycin, gemcitabine, epidermal growth factor receptor (EGFR)-directed therapies, mechanistic target of rapamycin protein (MTOR) inhibitors and immune checkpoint inhibitors." (PMID 30326612, 2018). "In recent decades, molecular targeted therapy has demonstrated clinical efficacy in cancer patients, such as epidermal growth factor receptor tyrosine kinase inhibitors (EGFR‐TKIs) for advanced NSCLC patients with EGFR mutations." (PMID 30109777, 2018). "Our aim was to produce a mono-biotinylated single domain antibody (‘nanobody’) specific for the epidermal growth factor receptor (EGFR), which is overexpressed in many cancer cells." (PMID 30348204, 2018). "R-611 was designed to target EGFR, a receptor overexpressed and/or amplified in a variety of cancers, their metastases, and also widely expressed in non-cancer cells." (PMID 29966356, 2018). "Therapeutic agents targeting EGFR and ErbB2 are now currently used in treating a variety of cancers." (PMID 29348142, 2018).
cancer (continued). "TGFα and EGF stimulate EGFR to induce cell growth signaling in normal condition and are involved in invasive and metastatic condition of cancers." (PMID 30774817, 2018). "Accumulating evidence suggests that EGFR possesses kinase-independent pro-survival functions, and that cancer cells are more vulnerable to reduction of EGFR protein than to inhibition of its kinase activity." (PMID 29358623, 2018). "Galectin-3 promotes a self-fueling loop generating cancer stem cells (CSCs) through stimulation of EGFR, which, in turn, leads to increased c-Myc protein stability and Sox2 transcription." (PMID 29462882, 2018). "Oncogenes in cancers, such as EGFR in GBM, are likely to be highly expressed, and RNA-seq naturally provides better coverage of such genes than WES, and hence higher statistical confidence to detect variants." (PMID 30083469, 2018). "Instead of driving cancer cell survival pathways that can be inhibited by targeted therapies (e.g. epidermal growth factor receptor, vascular endothelial growth factor receptor), NQO1 activates ARQ 761 to exert cytotoxic effects via oxidative stress." (PMID 30318513, 2018). "We extended this observation that peptide 327 also suppressed the viability of cancer cells, blocked EGFR signal pathway and reduced the expression of downstream targets." (PMID 29515106, 2018). "Amplification of EGFR, PIK3CA, and BRAF, and deletion of CDKN2A, RB1 and EP300 were strongly associated with shorter patient survival times in four or more cancer types each." (PMID 30526857, 2018). "In both cancer and normal mammary epithelial cell lines, cIAP1 depletion resulted in a marked drop of EGFR levels, which further decreased upon stimulation with EGF." (PMID 29674627, 2018). "We showed earlier the efficiency of MNT DTox-HMP-NLS-EGF for its EGFR-mediated cell recognition and endocytosis and endosome escape, along with accumulation of the MNT in the cell nuclei of target cancer cells with EGFR overexpression in vitro and in vivo." (PMID 30510514, 2018). "The epidermal growth factor receptor (EGFR) is frequently overexpressed in cancers of patients with poor prognosis and is found in 80–90% of HNSCC." (PMID 30192802, 2018). "In TNBC, even in the presence of EGFR inhibitors, cancer cells exhibit perpetual phosphorylation of this receptor, which correlates with the resistance to tyrosine kinase inhibitors (TKI)." (PMID 30227653, 2018). "The collective data in this report indicate that upregulation of ST6Gal-I, a common feature of cancer cells, promotes heightened activation of EGFR as well as resistance to gefitinib-induced cell death." (PMID 29402301, 2018). "Blocking EGFR signaling by monoclonal antibodies or tyrosine kinase inhibitors induces apoptosis and reduces proliferation in vitro and in cancer xenograft models." (PMID 29987260, 2018). "In this study, we adopted atomic force microscopy to measure the mechanical properties of cancer cells following cetuximab treatment and the biomechanical properties of cetuximab and epidermal growth factor receptor interactions." (PMID 35541738, 2018). "For example, the cancer growth inhibitory effects of anti-parallel bsDbs with specificity for EGFR and CD3 were affinity-dependent in each molecule and were highest for LH-ordered constructs." (PMID 29568402, 2018). "This work demonstrates nanoparticle co-delivery of a therapeutic radionuclide plus a ruthenium-based radiosensitizer can achieve combinational and targeted therapeutic effects in cancer cells that overexpress EGFR." (PMID 29808844, 2018). "Our findings of OGN-dependent regulation of EGFR internalization add alternative mechanism to a growing body of evidence that highlights the importance of receptor endocytosis in cancer progression." (PMID 29499765, 2018).
cancer (continued). "For immune-based capture of cancer cells based on microfluidic methods, EGFR has been used as a target marker in a few studies." (PMID 30104638, 2018). "The epidermal growth factor receptor (EGFR) belongs to the family of receptor tyrosine kinases and is one of the most frequently overexpressed proteins in malignant tumors." (PMID 29888317, 2018). "This challenge is underscored by our own clinical experience of the limited applicability of targeted anti-cancer therapies such as the EGFR inhibitor Cetuximab in RDEB-SCC patients." (PMID 30194425, 2018). "Here the authors identify two modes of ERK activity generated independently from EGFR and ErbB2 receptor and whose balance in cancer is shifted by Wnt pathway activation, resulting in enhanced sensitivity to EGFR inhibitors." (PMID 29872037, 2018). "These observed growth-inhibitory actions of PI3K/AKT and EGFR are surprising, as these pathways are conventionally considered to provide survival-promoting cues for diverse types of cancer cells." (PMID 29358688, 2018). "Due to EGFR’s association with malignancies, it has become the target for an expanding class of anti-cancer therapies, such as gefitinib (Iressa) and erlotinib (Tarceva), which are the first-generation EGFR-TKIs." (PMID 30337598, 2018). "The EGFR is a validated therapeutic target in various cancers, employing monoclonal antibodies and tyrosine kinase inhibitors." (PMID 30348204, 2018). "In this study, we applied this polymer CTC chip to capture of cancer cells expressing epidermal growth factor receptor (EGFR)." (PMID 30104638, 2018). "NTSR1 regulates the EGFR transactivation in numerous cancers including colon, foregut neuroendocrine, lung, and prostate cancer." (PMID 30008698, 2018). "Third, it was shown that TNBC cell lines are characterized by a profile of gene expression similar to those of k-Ras or EGFR-mutant cancers and exhibit upregulation of pMEK and pERK." (PMID 30227653, 2018). "Although integrin β4 knockdown inhibited the activation of p-FAK, it significantly promoted the activation of p-EGFR, indicating that there is a mutual modulation between integrin β4 and EGFR to induce the proliferation and growth of cancers." (PMID 29618949, 2018). "Alternatively, as shown in the reported studies, MMP9 enhance EGFR expression via PI3K/AKT pathways in cancers of the lung, ovaries, breast and brain." (PMID 30134822, 2018). "Aberrant activation of EGFR in cancer cells as a result of gene copy number amplification, protein overproduction, or point mutations leads to unregulated proliferation, malignant transformation, invasion, metastasis, and resistance to apoptosis." (PMID 30227653, 2018). "This dysregulation increases the basal Src activity, resulting in the activation of Src effectors such as ERK, EGFR, Akt and FAK, all of which are implicated in cancer progression." (PMID 30120256, 2018). "In various types of cancer, including tumors of the head, neck, lung, and breast and colorectal tumors, the ErbB family of receptors (EGFR/HER1/ERBB1, HER2/neu/ERBB2, HER3/ERBB3, and HER4/ERBB4) is unregulated, producing an inappropriate cell stimulation." (PMID 30670929, 2018). "Studies show that treatment of cancer cells with EGFR-therapeutics (e.g., erlotinib, gefitinib, and cetuximab) down-regulated the levels of HIF-1α protein." (PMID 30513863, 2018). "Flow cytometry and fluorescence microscopy studies have consistently shown that the quenched Pan-ICG conjugate can be activated only after binding to EGFR on the surface of cancer cells, and cannot activate EGFR-negative lymph node metastases." (PMID 29856819, 2018). "Although many types of cancer appear to depend upon upregulation of EGFR function for disease progression, EGFR tyrosine kinase inhibitors (TKI) have shown only transient clinical efficacy." (PMID 29358623, 2018). "Dysregulation of the EGFR is a common mechanism in cancer progression especially in non-small cell lung cancer (NSCLC)." (PMID 29548337, 2018).